ENSG00000269842 (novel transcript)
Gene: Long non-coding RNA gene on chromosome 19 (53,648,043 to 53,764,199, forward strand). Ensembl gene ENSG00000269842.
Gene Ontology:
Biological process: miRNA-mediated post-transcriptional gene silencing